INS (insulin)
Diseases named in the same sentence as INS in open-access papers (continued):
Sharing a sentence is not in itself a finding about the gene and the disease.
diabetes (continued). "Interestingly, insulin specificity and affinity of the recombinant antibodies (recAbs) was associated with the Vκ4 family, especially Vκ4-74, independent of the diabetes risk of the mouse strain." (PMID 36275764, 2022). "While this is a possible contributor, we believe it may be less likely than a reduction in insulin clearance per se, as it is known that beta-cell defect, not oversecretion, is related to diabetes risk." (PMID 35163746, 2022). "The correct diagnosis of pancreatogenic diabetes is vital, as, in contrast with T2DM, it is more frequently associated with poor glycemic control, inducing the so-called “brittle diabetes”, and the need for insulin therapy is often present earlier in the disease’s course." (PMID 35625546, 2022). "AGH may occur during pregnancy and should be considered in the context of chronic poorly controlled overt diabetes, rapid normalization of maternal blood glucose levels following high dose insulin therapy, and unexplained new-onset serum transaminase levels elevation." (PMID 40041230, 2022). "Therefore, losing weight and improving insulin sensitivity may be good ways to avoid higher insulin response and prevent the development of diabetes." (PMID 35090539, 2022). "Diabetes mellitus (DM) is a group of metabolic disorders manifested by chronic hyperglycemia which occurs as a result of a defect in insulin secretion, insulin action or both." (PMID 35334035, 2022). "Diabetes mellitus (DM) is a chronic metabolic disorder characterized by elevated blood glucose levels resulting from disturbances in insulin secretion, utilization, or both." (PMID 35164238, 2022). "Adult-onset diabetes (> 30 years at diagnosis), presence of diabetes-associated autoantibodies, and absence of the requirement of insulin requirement for at least 6 months after diagnosis are the key current diagnostic criteria for LADA from the insight of an international expert panel." (PMID 36090989, 2022). "IGF-2 has high structural homology with insulin and is produced in the liver and other tissues; symptoms similar to Type 2 diabetes (including hyperinsulinemia and mild hyperglycemia) are observed in transgenic mice that overexpress IGF-2 in β-cells causing β-cell dysfunction that leads to diabetes." (PMID 35804599, 2022). "Reduced insulin secretion or diminished tissue insulin sensitivity are the hallmarks of diabetes mellitus (DM), a metabolic illness that affects the metabolism of carbohydrates, lipids, and proteins." (PMID 36249656, 2022). "Hence, hypoxia-resistant insulin-producing cells could represent a future promising candidate for ameliorating the pathological indices of diabetes mellitus." (PMID 36248064, 2022). "Although old rats in the present study did not present full picture of frank diabetes mellitus, they exhibited some criteria of age-related diabetic changes, manifested as a significant decrease in serum insulin level compared to adult group, associated with high FPG and low HOMA-B%." (PMID 35416562, 2022). "Diabetes mellitus (DM) is a group of common metabolic disorders characterized by varying levels of disturbance in insulin secretion, dependence on insulin, and increase in blood glucose concentration." (PMID 36132073, 2022). "Drugs that lower insulin secretion in people without diabetes also cause weight loss." (PMID 35896818, 2022). "This tissue damage could further impair the insulin released, deteriorating the diabetes condition." (PMID 36438767, 2022). "Diabetes Mellitus (DM) is a chronic metabolic disorder that results due to decreased or very minor insulin secretion leading to increased sugar levels in the blood." (PMID 36364338, 2022). "Diabetes mellitus (DM) is a metabolic disorder resulting from a defect in the secretion or operation of insulin." (PMID 36420090, 2022).
diabetes (continued). "Therefore, patients admitted to hospitals for severe COVID-19 may need modifications to their diabetes therapy, including the withdrawal of ongoing treatments and the initiation of insulin therapy." (PMID 35530861, 2022). "However, as young people with T1DM have lower BMI on average than those with T2DM, our finding that obesity is associated with elevated glucose, insulin and diabetes is unlikely to be impacted by this potential bias." (PMID 35954531, 2022). "Diabetes management which avoids hypoglycemia in T1D requires frequent decisions in insulin dosing that impact glucose levels and insulin sensitivity, leading to day-to-day variability of glucose levels and insulin requirements, resulting in a high burden of diabetes management." (PMID 35351095, 2022). "However, very high insulin levels do not allow compensation for the deficiency in glucose uptake and lead to insulin resistance and diabetes." (PMID 37746194, 2022). "Insulin resistance (IR), which leads to type 2 diabetes mellitus and several metabolic disorders, is characterized by the decreased ability of insulin-target tissues (such as skeletal muscle, liver, and adipose tissue), to respond to the stimulation by insulin." (PMID 36120365, 2022). "The plot suggests that during the first day of the ICU stay, perhaps unsurprisingly, diabetic patients are more likely to receive a large amount of administered insulin (P < 0.001 using a χ2 test for the null hypothesis that diabetes and insulin amount are independent)." (PMID 37318234, 2022). "Diabetes (DM) is a chronic metabolic disease characterized by high blood glucose level, which occurs as a result of deficit in insulin and/or insulin resistance." (PMID 35301410, 2022). "Therefore, it is possible that glycemic variability may facilitate the development of diabetes via altered insulin sensitivity." (PMID 35170854, 2022). "In addition, it can affect glucose metabolism by regulating insulin sensitivity, glycogen storage, glucose uptake, and gluconeogenesis enzymes; fatty acid oxidation, synthesis, and energy expenditure; pharmacodynamics and pharmacokinetics of diabetes drugs." (PMID 36355175, 2022). "Moreover, from the 109 people with diabetes alive after one year (from a total of 189 at discharge), 10% reported impaired glycemic control, 9,2% had to intensify oral therapy, 4,6% required new prescription of insulin." (PMID 35250853, 2022). "This stabilization effect of insulin on atrial fibrillation could probably be stretched on SAN tissues since they express the Nav1.5 channel, and since arrhythmic SANCs are a hallmark of diabetes in animal models." (PMID 35872997, 2022). "American Diabetes Association(ADA) defines diabetes mellitus as“a general term for a group of metabolic disorders with disrupted carbohydrate, fat, and protein metabolism that results from defects in insulin secretion, insulin action, or both commonly characterized by elevated blood glucose”." (PMID 36001578, 2022). "This may have resulted in delayed diabetes diagnosis, delayed insulin delivery, more episodes of diabetic ketoacidosis (DKA) and hyperglycemia, and admission to the pediatric intensive care unit (PICU); families also experienced fear of contracting COVID-19 infection while obtaining care." (PMID 36620301, 2022). "Correlations between diabetes, inflammation, and oxidative stress are well established, where the suppression of inflammation, pro-inflammatory cytokines, and ROS production stimulates the insulin signaling pathway to promote insulin secretion when Syzygium extracts are administered." (PMID 35684249, 2022). "However, whether insulin treatment improves depression in patients with diabetes remains controversial." (PMID 36552776, 2022).
diabetes (continued). "Literature suggests that effective modulation of energy metabolism and insulin signaling through the regulation of AMP-activated protein kinase (AMPK) or phosphoinositide 3-kinase/protein kinase B (PI3K/AKT) pathways appears to reverse some devastating outcomes of diabetes." (PMID 35899107, 2022). "In cohort 2 of patients with extreme obesity, all those with high VAT-E2F1 showed a diabetes-complicated obesity phenotype and higher expression of miRNA-206 and miRNA-210-5p, which also correlated with fasting glucose levels (both miRNAs) and fasting insulin (miRNA-210-5p)." (PMID 36231008, 2022). "Baseline disordered eating will be assessed with the Diabetes Eating Problem Survey-Revised (DEPS-R); this 16-item tool is used to assess general and diabetes-specific disordered eating behaviours including weight loss, food restriction, insulin misuse, and vomiting." (PMID 36404842, 2022). "It has been suggested that bacosine works in a way similar to insulin and that its antihyperglycemic activity might be attributed to the increase in the consumption of peripheral glucose as well as protect against oxidative damage in alloxan induced diabetes." (PMID 35282429, 2022). "Indeed, it is possible that GDM women who have ready access to interventions and medical care for their diabetes (i.e., dietary advice, glucose monitoring, insulin therapy etc.)may be less likely to develop adverse mental health outcomes." (PMID 35305655, 2022). "It is divided into two types: Type 1 Diabetes Mellitus (T1DM), where there is an absolute or near absolute deficiency of insulin, and Type 2 Diabetes Mellitus (T2DM), where there is resistance to insulin with an inadequate compensatory increase in insulin secretion." (PMID 35846869, 2022). "Diabetes mellitus (DM) is a metabolic disorder with persistently high blood glucose levels, resulting from an impairment of insulin production and insulin resistance." (PMID 35742837, 2022). "A condition of less-than-normal insulin levels can have an impact on glycolysis, decrease the rate of adenosine diphosphatase phosphorylation, and slow down adenosine triphosphatase resistance, which could, in turn, lead to diabetes fatigue." (PMID 36048792, 2022). "Whether ratios of proinsulin intermediates to fully processed insulin might be indicative of diabetes subsets, severity or prognosis is an open question for precision approaches to diabetes diagnosis and management, which we hope the newly established method will help to address." (PMID 36242807, 2022). "In addition, the high proportion of ‘dosage too low’ may also be due to the underuse of standard diabetes treatment guidelines, and dose calculation for insulin-based regimens was majorly based on assumed weight." (PMID 35767589, 2022). "Diabetes mellitus (DM) is a group of metabolic diseases characterized by increased blood glucose level and inability to produce and/or use insulin." (PMID 35069742, 2022). "Furthermore, our findings that SGLT-2is were associated with lower all-cause mortality, independent of diabetes duration and insulin use, provided additional support for the notion that our observed association was probably a drug effect." (PMID 35894858, 2022). "Furthermore, the administration of SelP-neutralizing antibodies could improve insulin secretion and glucose intolerance in a mouse model of diabetes." (PMID 36438755, 2022). "Additionally, the findings illustrate that diabetes-related complications, old age, obesity, duration of diabetes, insulin and oral anti-diabetic medication use were the major predictors that require comprehensive intervention strategies to enhance the HRQoL of patients with diabetes." (PMID 35180266, 2022). "Another explanation might be related to the abnormal insulin modification in diabetes patients." (PMID 35936393, 2022).
diabetes (continued). "The continuous absorption of dextrose leads to hyperglycemia, exacerbation of diabetes mellitus (DM), hyperlipidemia, obesity, malnutrition, and titration of insulin dose in DM patients." (PMID 35329948, 2022). "One possible explanation may be that prostate cancer patients with diabetes may represent a unique subpopulation in which the PSMA expression correlates with both the androgen receptor expression as well as insulin and the insulin growth factor receptor expression." (PMID 35330410, 2022). "Indeed, a recent meta-analysis found that pre-, pro- and symbiotic-supplementation reduces fasting insulin levels, hyperinsulinaemia and circulating AGEs in individuals with diabetes, suggesting the link between the microbiome, glucose homeostasis and AGE burden is an important one." (PMID 35807857, 2022). "Furthermore, another study demonstrated that high plasma residual cholesterol was overproduced in the insulin-resistant status, and it may have a key role in the etiology of coronary artery disease in patients with diabetes." (PMID 36324177, 2022). "Diabetes Mellitus (DM) is defined by the presence of hyperglycemia due to a deficit of insulin production and/or resistance." (PMID 36013381, 2022). "This study assessed whether a diabetes-focused inpatient discharge order set (DOS) with nurse follow-up calls can improve postdischarge outcomes compared with enhanced standard care (ESC) among hospitalized patients with insulin-requiring T2D." (PMID 35881437, 2022). "Also, the patients receiving biologic DMARDs for JIA require less insulin therapy for diabetes." (PMID 34999914, 2022). "An intranasal treatment with insulin could be a promising perspective to prevent cognitive deficiencies induced by diabetes regardless of patient age." (PMID 35958117, 2022). "In addition, one of the unknown cases was an individual with diabetes mellitus type 1 where insulin analysis was requested by the forensic pathologist at the time of autopsy; however, sample quality impeded the analysis of insulin." (PMID 36676928, 2022). "Here, the authors show adding exenatide to basal insulin in early type 2 diabetes does not further enhance underlying pancreatic beta-cell function or the capacity to achieve diabetes remission, but may yield on-treatment glycemic benefits." (PMID 36244997, 2022). "Diabetes mellitus (DM) is a metabolic disorder characterized by hyperglycemia that results from a defect in insulin secretion, insulin action, or both." (PMID 36239103, 2022). "Furthermore, another cohort study on the risk of stroke in elderly patients with diabetes and patients with no diabetes also showed that elevated fasting insulin levels are a risk factor for stroke." (PMID 35242879, 2022). "Diabetes mellitus (DM) is a complex metabolic disorder which is characterized by high blood glucose levels, due to inadequate insulin secretion by the pancreas or inability of target cells to reuptake glucose from the blood." (PMID 35127954, 2022). "Several mechanisms for the link between diabetes and dementia have been proposed including brain metabolic dysfunction as a driver for AD pathology, with impairments in insulin transport through the blood-brain barrier, insulin signaling, and resultant decreased cerebral glucose utilization." (PMID 35280286, 2022). "Diabetes mellitus (DM) is a common metabolic disease due to abnormal insulin secretion or insulin action." (PMID 36042445, 2022). "Our work suggests that it may be of use in diabetes, repurposed to increase insulin secretion." (PMID 36251711, 2022). "In addition, the DR population revealed a longer duration of diabetes, higher HbA1c levels, a higher rate of insulin treatment, higher serum creatinine, a lower glomerular filtration rate, and lower HDL cholesterol levels compared to the non-DR group (all p < 0.05)." (PMID 36361470, 2022).
diabetes (continued). "This year marks the 100th anniversary of the isolation of human insulin and its successful administration to patients suffering from diabetes mellitus (DM)." (PMID 35454166, 2022). "Diabetes mellitus (DM) is a common metabolic disorder characterized by chronic hyperglycemia and altered metabolism of carbohydrates, fats, and proteins due to defects in insulin secretion and action, or both." (PMID 35148683, 2022). "For patients with diabetes, there are changes in glycemic variability patterns which are more pronounced in patients on insulin secretagogues and insulin therapy, which includes multiple daily injections (MDIs) of insulin or continuous subcutaneous insulin infusion (CSII)." (PMID 35433783, 2022). "Furthermore, we showed its potential to improve insulin activity in a diabetes mouse model." (PMID 35350789, 2022). "Diabetes mellitus (DM) is a prevalent chronic metabolic disorder characterized by elevated plasma glucose levels due to inadequate insulin synthesis and/or enhanced insulin resistance." (PMID 35855231, 2022). "In patients with diabetes, for example, the use of insulin could affect the level of serum albumin." (PMID 36212479, 2022). "IDE deficiency leading to cytoskeleton disarrangements and ciliogenesis impairment in pancreatic α-cells, and most likely in β-cells, results in dysregulation of hormone secretion and cellular immaturity, which maybe triggering insulin and glucagon imbalance seen in diabetes." (PMID 35832432, 2022). "Therefore, inhibition of UCP2 or AldB might be a promising therapeutic strategy to improve insulin secretion in patients with diabetes." (PMID 35800776, 2022). "The share of participants reporting a longer duration of diabetes and the use of insulin or other injectable was substantially higher in the “GP & podiatrist” profile than in the “GP only” one, which could explain the involvement of the diabetologist concomitantly with the GP." (PMID 35498410, 2022). "Diabetes Mellitus (DM) is a debilitating metabolic disorder characterized by impaired insulin function, leading to chronic hyperglycemia." (PMID 35610696, 2022). "However, baboons present specific challenges related to their size and high insulin demand; indeed, the basal daily exogenous insulin requirements post diabetes induction of the animals used in this study were almost twice those reported for macaques used in similar studies." (PMID 35784286, 2022). "Hence, cytokine CRP and insulin expression in saliva at this age could potentially predict future progression to serious metabolic diseases, such as diabetes and cardiovascular diseases." (PMID 35757631, 2022). "Diabetes mellitus (DM) includes a cluster of metabolic conditions defined by hyperglycemia that can result from insufficient insulin secretion, defects in insulin action, or both." (PMID 35631171, 2022). "The stages are genetic predisposition; an action of the precipitating event; overt immunologic abnormalities with normal insulin release; progressive loss of insulin release with normal glucose level; overt diabetes with present C-peptide; and complete β-cell destruction (no C-peptide)." (PMID 35992113, 2022). "Moreover, besides the effects on glucose metabolism, luteolin may represent a potential treatment for diabetes, and it might even ameliorate the glucose uptake via restoring the insulin signaling in an insulin-resistance background." (PMID 35334812, 2022). "Furthermore, even though reduced bone mass was found in young subjects with moderate type 1 diabetes with metabolic control, the findings in the present study are related to severe diabetes (i.e., BG ≥ 300 mg/dL), thus, it is difficult to generalize to patients treated with insulin." (PMID 34440530, 2021). "However, hypoxia may also decrease insulin sensitivity and possibly exacerbate the danger of uncontrolled diabetes." (PMID 34337893, 2021).